CPSF1 (cleavage and polyadenylation specific factor 1)
Diseases named in the same sentence as CPSF1 in open-access papers:
CPSF1 is named in the same sentence as 28 diseases in open-access papers, as found by Europe PMC text mining. Sharing a sentence is not in itself a finding about the gene and the disease. The quoted sentences say what the papers report.
breast carcinoma (4 papers, 2013 to 2021). "We found that the MYC ChIP-seq signal is enriched at the CPSF1 promoter, in both keratinocytes as well as the breast cancer cell line MCF7." (PMID 33469008, 2021). "The depletion of CPSF1 or PABPN1 weakened cell proliferation, enhanced apoptosis, resulted in cell cycle redistribution and a reversion of APA events of genes associated with tumorigenesis, proliferation, metastasis and chemosensitivity in breast cancer." (PMID 32929364, 2020). "Therefore, exclusive interaction of CFIm25/CPSF1 complex with distal region of EGFR and AKT3 3′-UTR coding mRNA, would guarantee suppression of breast cancer progression." (PMID 32665581, 2020). "It was observed that the expression of several 3′-processing factors, including CPSF1 and CSTF2, were overall higher in breast cancer than normal cell lines, so this may be another important factor influencing APA pattern differences between MCF-7 and MCF-10A." (PMID 23437281, 2013).
lung carcinoma (4 papers, 2017 to 2022). "A tumor-specific increase in expression of histone deacetylases and CPSF1 was detected in lung cancer." (PMID 28634396, 2017). "Recently, several studies performed in cell lines have reported that CPSF1 may be related to lung cancer, ovarian cancer and prostate cancer, and CPSF1 was also shown to affect definitive haematopoietic stem cell survival in a screen of ENU-mutated zebrafish." (PMID 30689892, 2019). "In addition, we compared CPSF1 levels in primary lung SCCa, AdCa and normal lung, from which a significant increase of CPSF1 expression was detected in the lung cancer samples compared to normal lung." (PMID 28634396, 2017). "As an important component of APA, CPSF is usually upregulated in cancers, such as CPSF1 in HCC and ovarian cancer, CPSF3 in HCC, CPSF4 in colorectal and lung cancers, and CPSF7 in HCC." (PMID 36349192, 2022).
myopia (4 papers, 2019 to 2025). "Further studies of how the variant of CPSF1 is connected with high myopia are still needed." (PMID 40920702, 2025). "The CPSF1 gene is responsible for autosomal dominant Myopia-27 (MYP27), characterized by early-onset high myopia with increased axial lengths." (PMID 37628591, 2023). "Another group has reported multiple novel CPSF1 mutations that are associated with early-onset high myopia, although causality has not been investigated." (PMID 41463412, 2025). "However, the relationship between CPSF1 and human ocular diseases, including myopia, remains unknown." (PMID 30689892, 2019). "The relatively low transcription of CPSF1 in the human lens might be consistent with axial elongation of the eye rather than curvature myopia in the patients with eoHM in this study." (PMID 30689892, 2019).
prostate carcinoma (4 papers, 2019 to 2025). A carcinoma that arises from epithelial cells of the prostate gland. "Our work has highlighted GPI, PFKM, ALDOA, and PGK1 as key glycolysis-associated mRNAs that display CPSF1-dependent expression in prostate cancer cell lines." (PMID 39847481, 2025). "The selective growth inhibition of prostate cancer cells following CPSF1 knockdown was associated with impaired glycolysis and deregulated expression of glycolysis-regulating genes." (PMID 39847481, 2025). "To identify CPSF1-regulated pathways required for prostate cancer growth, we performed RNA sequencing (RNA-seq) on LNCaP, LNCaP95, and 22Rv1 cells with stable knockdown of CPSF1." (PMID 39847481, 2025). "In this study, we found that CPSF1 mRNA expression levels are elevated in CRPC tumors relative to primary prostate cancer and that high CPSF1 expression predicted shorter progression-free survival." (PMID 39847481, 2025). "Because CPSF1 is a core eukaryotic mRNA polyadenylation factor, we examined the role of CPSF1 in regulating global polyadenylation in prostate cancer." (PMID 39847481, 2025). "CPSF1-dependent targets included glycolytic genes, providing a mechanistic underpinning for impaired glycolysis in prostate cancer cells following CPSF1 inhibition." (PMID 39847481, 2025). "CPSF1 as well as mRNAs that are regulated by this mechanism are increased during prostate cancer progression, and the knockdown of CPSF1 inhibits the growth of prostate cancer cells but not benign epithelial prostate cells." (PMID 39847481, 2025). "In this work, we have identified CPSF1 as a key regulator of global APA in prostate cancer and shown that CPSF1 is required for the growth of androgen-dependent and androgen-independent prostate cancer cell lines." (PMID 39847481, 2025). "We found that the cleavage and polyadenylation specificity factor (CPSF) complex factor CPSF1 is upregulated in patients with advanced prostate cancer, with high CPSF1 expression correlating with worse progression-free survival." (PMID 39847481, 2025). "Collectively, this work identifies CPSF1 as a factor required for glycolytic output of prostate cancer cells." (PMID 39847481, 2025). "We next sought to examine the clinical relevance of these mechanisms identified in prostate cancer cell lines subjected to CPSF1 knockdown." (PMID 39847481, 2025). "Knockdown of CPSF1 selectively inhibited the growth of prostate cancer cells and reduced glycolytic output." (PMID 39847481, 2025). "Accordingly, these gene expression changes in clinical prostate cancer specimens are likely to occur via CPSF1-dependent alterations in the use of poly(A) sites located downstream of 3′ UTRs." (PMID 39847481, 2025). "We found that CPSF1 sustains levels of mRNAs encoding glycolysis regulators, highlighting a vulnerability in advanced prostate cancer that is independent of AR and AR-regulated pathways." (PMID 39847481, 2025). "An additional strategy for inhibiting CPSF1 in prostate cancer could be to interfere with CPSF1-mediated regulation of target mRNAs." (PMID 39847481, 2025). "Evaluating the changes in global poly(A) site usage in prostate cancer cells following CPSF1 knockdown revealed widespread usage of intergenic poly(A) sites distal to annotated 3′ UTRs, which lengthened 3′ UTRs and decreased levels of thousands of mRNAs, including key glycolysis genes." (PMID 39847481, 2025). "Thus, components of the machinery regulating mRNA cleavage and polyadenylation display altered expression in prostate cancer, with high CPSF1 correlating strongly with progression to metastatic CRPC." (PMID 39847481, 2025). "Therefore, CPSF1 and CPSF1-regulated mRNAs represent vulnerabilities that could be exploited therapeutically to inhibit glycolysis and the growth of prostate cancer cells." (PMID 39847481, 2025).
prostate carcinoma (continued). "Overall, our findings that the major effects of CPSF1 in prostate cancer cells are to repress intergenic poly(A) site usage and promote intronic poly(A) site usage reveal intricate mechanisms of gene expression regulation that are required for prostate cancer cell growth." (PMID 39847481, 2025). "We then examined somatic copy number variation (CNV) of these writers in prostate cancer and found that KIAA1429 and CPSF1 had a widespread frequency of copy number variation (CNV) gain." (PMID 36744180, 2022). "As expected, the stable knockdown of CPSF1 inhibited the growth of all three prostate cancer cell lines but, interestingly, had no inhibitory growth effect on RWPE-1 cells." (PMID 39847481, 2025). "Collectively, these data demonstrate that CPSF1 is necessary to maintain glycolysis in prostate cancer cells but CPSF1 overexpression is not sufficient to increase glycolytic output." (PMID 39847481, 2025). "We have found that CPSF1 knockdown leads to the selective inhibition of prostate cancer cell growth, but we have not identified the specific downstream target(s) of CPSF1 that explain these differential effects." (PMID 39847481, 2025). "Knockdown of CPSF1 inhibited the growth of prostate cancer cells but not that of a benign epithelial prostate cell line." (PMID 39847481, 2025). "These small-molecule inhibitors have not previously been used in prostate cancer cells and could provide another strategy to interfere with CPSF1-mediated regulation." (PMID 39847481, 2025). "We performed experiments in prostate cancer cell lines grown in vitro, which may not reflect the effects of gene regulation by CPSF1 in vivo." (PMID 39847481, 2025).
ovarian carcinoma (3 papers, 2019 to 2022). A malignant neoplasm originating from the surface ovarian epithelium. "Previous data established that CPSF1 may promote ovarian cancer, cell proliferation, and triple-negative breast cancer." (PMID 35282430, 2022).
chronic eosinophilic leukemia (2 papers, 2022 to 2025). "Factor interacting with PAPOLA and CPSF1 (FIP1L1), fused with platelet-derived growth factor receptor α (PDGFRα), has been linked to several hematologic malignancies (hypereosinophilic syndrome, chronic eosinophilic leukemia, systemic mastocytosis)." (PMID 35494081, 2022). "The most sensitive cell line was the chronic eosinophilic leukemia cell line EoL-1 (IC50 = 59 nmol/L), expressing a fusion gene of Factor Interacting with PAPOLA and CPSF1 (FIP1L1) and platelet-derived growth factor receptor α (PDGFRα)." (PMID 41199836, 2025).
head and neck squamous cell carcinoma (2 papers, 2020 to 2021). A squamous cell carcinoma that arises from any of the following anatomic sites: lip and oral cavity, nasal cavity, paranasal sinuses, pharynx, larynx, and salivary glands. "For example, CPSF1 promotes head and neck squamous cell carcinoma growth by regulating AS in cancer-associated genes, such as AKT2, HRAS, TGFBI, and UBE2C." (PMID 33748106, 2021). "In tumors, CPSF1 plays an oncogenic role in head and neck squamous cell carcinoma, ovarian cancer, and prostate cancer growth." (PMID 33748106, 2021).
hepatocellular carcinoma (2 papers, 2022 to 2023). A malignant tumor that arises from hepatocytes. "For example, the upregulation of CPSF1 in hepatocellular carcinoma (HCC) tissues is correlated with poor survival outcomes, and CPSF1 knockdown inhibits the proliferation and migration of HCC cells in vitro." (PMID 36349192, 2022).
viral infection (2 papers, 2009 to 2017). "The function for four targets have been ascribed (ROBO1, NLGN1, CPSF1, ATP8A1), but none of them have been linked with viral infection." (PMID 19788744, 2009).
autism (1 paper, 2018). Persistent deficits in social interaction and communication and interaction as well as a markedly restricted repertoire of activity and interest as well as repetitive patterns of behavior. "CPSF1 connects two epilepsy modules with features of NLF; meanwhile, PRPF8 connects epilepsy/CFD (EPI/CFD) with autism/CFD (AUT/CFD)." (PMID 30420816, 2018).
diabetes mellitus (1 paper, 2023). A metabolic disorder characterized by abnormally high blood sugar levels due to diminished production of insulin or insulin resistance/desensitization. "A DMR hypermethylated in the CPSF1 gene is a mediator of retinal vascular dysfunction in diabetes mellitus." (PMID 38093359, 2023).
gastric cancer (1 paper, 2025). A primary or metastatic malignant neoplasm involving the stomach. "Among them, NSDHL is positively regulated by CPSF1 and promotes the progression of gastric cancer." (PMID 39781570, 2025).
head and neck cancer (1 paper, 2020). A primary or metastatic malignant neoplasm affecting the head and neck. "In summary, we demonstrated that CPSF1 overexpression is a candidate oncogenic event in head and neck cancer." (PMID 32437477, 2020). "We found the overexpression of CPSF1 increased the tumorigenicity of the head and neck cancer cells using adherent cell line models as well as in vivo using xenograft models." (PMID 32437477, 2020). "Furthermore, to confirm the overexpression of CPSF1 in head and neck cancer primary tumors, we performed immunohistochemistry on as separate tissue microarray." (PMID 32437477, 2020).
lentivirus infection (1 paper, 2024). Virus diseases caused by the Lentivirus genus. "Since CPA factors are generally essential for cell survival, preliminary experiments (not shown) were done to establish the time needed after lentivirus infection to adequately deplete CPSF1 without causing cell death." (PMID 38587191, 2024).
squamous cell carcinoma (1 paper, 2020). A carcinoma arising from squamous epithelial cells. "S6 Fig shows representative non-neoplastic epithelia and squamous cell carcinoma cores from the tissue microarray with CPSF1 IHC staining." (PMID 32437477, 2020).
tumor (10 papers, 2011 to 2025). "According to other studies, SIAH1 is a tumor suppressor involved in PC pathogenesis by repressing CPSF1-mediated AR-v7 generation and is a key regulatory factor." (PMID 36744180, 2022). "Knockout of CPSF1 or PABPN1 reverses APA events of tumor-related genes in TNBCs, inhibits tumor cell proliferation, promotes apoptosis and redistributes the cell cycle." (PMID 34899345, 2021). "We found that CPSF1 mRNA expression was significantly increased in tumor tissues compared to that in normal tissues in the GEO Roessler liver dataset that was validated in 24 paired HCC samples collected at the SYSUCC." (PMID 33748106, 2021). "In 50 paired HCC tissues from the TCGA database, CPSF1 mRNA was relatively elevated in tumor tissues compared to the paired non-tumor tissues." (PMID 33748106, 2021). "Tumor growth in the nude mice injected with cells overexpressing CPSF1 was increased compared to empty vector-containing cells." (PMID 32437477, 2020). "We also found that the tumor volumes in the CPSF1 group were significantly larger than those in the empty vector group (p<0.05) at all time points." (PMID 32437477, 2020). "Interestingly, there is evidence that CPSF1 promotes tumor development by regulating APA events in triple-negative breast cancer (TNBC)." (PMID 34899345, 2021). "The overexpression of CPSF1 in tumor was confirmed by qRT-PCR and Western blot." (PMID 32437477, 2020). "Therefore, it was speculated that CPSF1 overexpression leads to abnormal splicing of oncogenes and promotes tumor occurrence and development." (PMID 34899345, 2021). "Some pathways are tumor-suppressive in nature and underwent APA lengthening coupled with decreased gene expression, supporting the idea that CPSF1 amplification represses these pathways through APA." (PMID 41463412, 2025). "The RMPs upregulated in tumours or showing a positive correlation with poor outcomes usually gained more CNVs, such as ADAR, CPSF1, IGF2BP1, and YTHDF1." (PMID 36118888, 2022). "In this study, we report for the first time that CPSF1, the major component of CPA, is upregulated in HCC compared to adjacent non-tumor tissues." (PMID 33748106, 2021). "In this study, we performed shRNA pooled library screening and identified CPSF1 and PABPN1 as key C/P factors involved in tumor proliferation." (PMID 32929364, 2020). "Statistical analysis revealed relatively higher expression of CPSF1 in tumor samples than in paired non-tumor samples." (PMID 33748106, 2021). "The gene expression of CPSF1 in the tumor samples in the TCGA HPV negative samples and positive samples was higher than normal samples." (PMID 32437477, 2020). "Furthermore, a pooled shRNA library screening identified CPSF1 and PABPN1, two alternative C/P factors, as potential targets of TNBC linking APA to tumor proliferation." (PMID 32929364, 2020). "In addition, we established CPSF1 and PABPN1 as key C/P factors involved in tumor proliferation and APA regulation in TNBC." (PMID 32929364, 2020).
cancer (9 papers, 2017 to 2025). A tumor composed of atypical neoplastic, often pleomorphic cells that invade other tissues. "In HNSCC, we previously determined that CPSF1 promotes aberrant splicing of cancer-associated genes and induces HNSCC cell proliferation and tumorigenicity." (PMID 37434235, 2023). "Twelve cancer-associated gene sets were identified in the CPSF1 overexpression dataset, including MISHRA_CARCINOMA_ASSOCIATED_FIBROBLAST_UP, RICKMAN HEAD_AND_NECK_CANCER_D, and SMID_BREAST_CANCER_RELAPSE_IN_LUNG_UP." (PMID 32437477, 2020). "Finally, we performed ssGSEA analysis in each dataset to determine the gene sets altered by aberrant CPSF1 expression, and defined multiple cancer-associated gene sets in association with CPSF1 dysregulation." (PMID 32437477, 2020). "The involvement of CPSF1 in various human diseases, including cancers and ocular disorders has been studied, but its role in TB susceptibility remains unexplored." (PMID 38515745, 2024). "The exploration about the effects of circ-CPSF1 to cancer patients suffering radiotherapy is needed." (PMID 36671487, 2023). "Other cancer model organism and cancer cell after radiation should been considered to complete the potential of circ-CPSF1." (PMID 36671487, 2023). "In particular, genes known to be associated with cancer such as LAMC2, UBE2C, AKT2, AKT2, BOK, MAP4, and FANCD2 were noted to be aberrantly spliced, indicating that the aberrant expression of CPSF1 significantly altered the ASEs of oncogenes in each dataset." (PMID 32437477, 2020). "Understanding the mechanism of CPSF1-regulated poly(A) site selection could reveal sequence elements and factors that maintain a conserved function in poly(A) site cleavage and uncover therapeutic targets that are required for the growth and progression of various cancers." (PMID 39847481, 2025). "Because TNBC is a highly proliferative cancer, we reasoned that TNBC cell lines might be sensitive to changes in the CPSF1 and PABPN1 levels." (PMID 32929364, 2020). "We found circ-CPSF1 is detrimental to the longevity and reproduction of C. elegans via affecting ROS production and DDR pathway in the context of radiation exposure, which might provide new insight for cancer radiation." (PMID 36671487, 2023).
infection (3 papers, 2015 to 2024). The state of being infected such as from the introduction of a foreign agent such as serum, vaccine, antigenic substance or organism. "Little research has focused on CPSF3, but like CPSF1, it is thought to be involved in mRNA processing and may contribute to the regulation of gene expression in response to diverse pathogenic microorganisms, such as Toxoplasma gondii, Plasmodium falciparum, and Cryptosporidium infection." (PMID 38515745, 2024). "We successfully constructed stable cell lines with CPSF1-knockdown using lentivirus shRNA infection." (PMID 32929364, 2020). "Several infection-induced SUMO targets also are involved in mRNA maturation events, such as 3′ end pre-mRNA processing (CPSF1, CPSF2, FIP1L1, RBBP6, and WDR33), splicing (CLASRP, SFPQ, and ZRANB2), and nuclear RNA quality control (ZC3H18, ZCCHC7, and PAPD5)." (PMID 26549460, 2015).
CPSF1 also shares sentences with these, for which no sentence is quoted: colorectal cancer (1 paper); epilepsy (1); glaucoma (1); hypereosinophilic syndrome (1); leukemia (1); mastitis (1); retinal degeneration (1); Retinal dystrophy (1); systemic mastocytosis (1); triple-negative breast carcinoma (1).